PSMF1 (proteasome inhibitor subunit 1)
Description:
Plays an important role in control of proteasome function. Inhibits the hydrolysis of protein and peptide substrates by the 20S proteasome. Also inhibits the activation of the proteasome by the proteasome regulatory proteins PA700 and PA28.
Synonyms: PI31
Tractability: PROTAC: ubiquitination databases record sites on it; its protein half-life has been measured.
Gene: Protein-coding gene on chromosome 20 (1,113,240 to 1,189,415, forward strand). Ensembl gene ENSG00000125818.
Subcellular location: Cytoplasm; Endoplasmic reticulum
Subcellular location (Human Protein Atlas): Cytosol
Pathways (Reactome):
Metabolism of proteins: Proteasome assembly
Gene Ontology:
Molecular function: proteasome binding; protein binding; protein heterodimerization activity; protein homodimerization activity; endopeptidase inhibitor activity
Biological process: negative regulation of proteasomal protein catabolic process; ubiquitin-dependent protein catabolic process; proteasome-mediated ubiquitin-dependent protein catabolic process
Cellular component: cytosol; endoplasmic reticulum; membrane; perinuclear region of cytoplasm; proteasome core complex; cytoplasm
Genetic constraint (gnomAD): Loss-of-function variants: 30 observed, 29.43 expected, observed/expected ratio (o/e) 1.02, 90% interval 0.76 to 1.38. The upper end of that interval is the gene's LOEUF score, 1.38, which puts it in group 5 of 6, group 1 being the genes least tolerant of losing a copy. Missense variants: 344 observed, 368.42 expected, observed/expected ratio (o/e) 0.93, 90% interval 0.85 to 1.02. Synonymous variants: 134 observed, 147.61 expected, observed/expected ratio (o/e) 0.91, 90% interval 0.79 to 1.05.
Homologues: Orthologues: chimpanzee PSMF1 (99% identical), macaque PSMF1 (98% identical), rabbit PSMF1 (90% identical), guinea pig PSMF1 (90% identical), rat Psmf1 (87% identical), pig PSMF1 (85% identical), mouse Psmf1 (84% identical), dog PSMF1 (73% identical), zebrafish psmf1 (51% identical), tropical clawed frog psmf1 (44% identical), Drosophila melanogaster PI31 (27% identical), Drosophila melanogaster CG12729 (13% identical).
Diseases named in the same sentence as PSMF1 in open-access papers:
PSMF1 is named in the same sentence as 23 diseases in open-access papers, as found by Europe PMC text mining. Sharing a sentence is not in itself a finding about the gene and the disease. The quoted sentences say what the papers report.
Parkinson disease (3 papers, 2025 to 2026). A progressive degenerative disorder of the central nervous system characterized by loss of dopamine producing neurons in the substantia nigra and the presence of Lewy bodies in the substantia nigra and locus coeruleus. "A recent discovery is the proteasome inhibitor subunit 1 (PSMF1) variants leading to early-onset Parkinson's disease with disruption of the mitochondria integrity (morphology, potential, and fragmentation)." (PMID 41179085, 2025).
bladder urothelial carcinoma (1 paper, 2022). "ANXA8L1 (kidney renal papillary cell carcinoma) and CYP4B1 (lung adenocarcinoma and bladder urothelial carcinoma) were highly expressed at the early stage of these cancers, but PSMF1 was highly expressed in stage III stomach adenocarcinoma." (PMID 35807355, 2022).
cerebral malaria (1 paper, 2025). A sequestration of Plasmodium falciparum in the brain, which can cause coma and/or seizures. "A recent study applied network analysis and differential expression to whole-blood profiles, highlighting nine key host genes (including MBP, SAMSN1, PSMF1, SLC39A8) strongly linked to cerebral malaria." (PMID 41002937, 2025).
cholangiocarcinoma (1 paper, 2022). A carcinoma that arises from the intrahepatic biliary tree (intrahepatic cholangiocarcinoma) or from the junction, or adjacent to the junction, of the right and left hepatic ducts (hilar cholangiocarcinoma). "The results indicated that ANXA8L1 (cholangiocarcinoma), PSMF1 (stomach adenocarcinoma) and TNS4 (head and neck squamous cell carcinoma, lung squamous cell carcinoma, rectum adenocarcinoma, stomach adenocarcinoma) were highly expressed in these cancers." (PMID 35807355, 2022).
co-infection (1 paper, 2023). "Interestingly, the expression level of proteasome inhibitor subunit 1 (ZmPI31), a key gene that inhibits the maturation of the 20S proteasome to the 26S proteasome, was upregulated in single infection and co-infection, and the results of RT–qPCR were consistent with the transcriptome." (PMID 37175719, 2023).
malaria (1 paper, 2021). Malaria is a serious and sometimes fatal disease caused by a parasite that commonly infects a certain type of mosquito which feeds on humans. "Besides, the other identified key gene, PSMF1 and EIF3B, have also been reported associated with malaria in previous studies." (PMID 33942992, 2021). "Within the nine genes, five genes (MBP, SAMSN1, PSMF1, SLC39A8, and EIF3B) were previously found to be involved in malaria, and the remaining four genes (SMPDL3A, FABP5, SPSB3, and SHARPIN) were identified for the first time in the current study." (PMID 33942992, 2021). "Conversely, the other five key genes (MBP, SPSB3, PSMF1, SHARPIN, and EIF3B) were negatively correlated with malaria severity and decreased in CM." (PMID 33942992, 2021). "SAMSN1, SLC39A8, SMPDL3A, and FABP5 were positively correlated with malaria phenotype/severity and showed an upregulation in the CM group compared with healthy controls, while MBP, SPSB3, PSMF1, SHARPIN, EIF3B were negatively correlated with malaria severity and downregulated in the DEG." (PMID 33942992, 2021).
tumor (3 papers, 2008 to 2024). "The second module (M2) was composed of multiple metabolism-relevant phosphoproteins like PGK1, PSMF1, PRDX1, and TOM1, they showed lower expressions in the tumor tissues, especially the high RR tumor tissues." (PMID 38609408, 2024).
PSMF1 also shares sentences with these, for which no sentence is quoted: cancer (4 papers); breast carcinoma (2); glioma (2); amyotrophic lateral sclerosis (1); head and neck squamous cell carcinoma (1); hepatoma (1); infection (1); Insulin resistance (1); lung adenocarcinoma (1); Lung Squamous Cell Carcinoma (1); Obesity (1); Parkinsonism (1); rectum adenocarcinoma (1); stomach adenocarcinoma (1); type 1 diabetes (1); type 2 diabetes (1).